INS (insulin)
Diseases named in the same sentence as INS in open-access papers (continued):
Sharing a sentence is not in itself a finding about the gene and the disease.
Stroke (continued). "It has been observed also that glycaemic control in the first days after stroke can improve the complication rate, although, when an intensive insulin treatment is used, this improvement is not so clear." (PMID 31052350, 2019). "The following variables were selected based on the results of the Cox proportional hazards model and clinical relevance: age, history of CHF, history of hypercholesterolemia, history of stroke/TIA, serum creatinine, insulin use, myocardial jeopardy index, and HbA1c." (PMID 31093573, 2019). "Compared with those not experiencing stroke, those who did were less likely to be treated with lipid lowering therapy but more likely to be taking nitrates, anti-platelet therapy, and insulin." (PMID 28426886, 2017). "Overall, 891 (2.3%) patients had at least one event of non-fatal stroke during follow-up, with a rate (per 1000 person years) of 4.85; 90% (n = 803) of events occurred in the insulin group." (PMID 25616979, 2015). "The post-stroke delay of MRI had a non-significant effect on ADCabs values (p = 0.10), and the insulin regimen had no detectable effect (p = 0.70)." (PMID 25793765, 2015). "They found that fasting insulin levels, but not fasting glucose or glycated hemoglobin levels, were associated with CHD and stroke, even after allowing for other factors that affect cardiovascular disease risk such as smoking and physical activity." (PMID 17760500, 2007). "Metformin monotherapy may reduce stroke risk, while dipeptidyl peptidase 4 inhibitors, sodium-glucose co-transporter 2 inhibitors, and insulin do not seem to affect the incidence of stroke." (PMID 39407846, 2024). "However, they found that high fasting insulin levels have no role in increasing the likelihood of stroke, which is similar to our finding." (PMID 39347227, 2024). "While pre-meal measurements are useful for determining the insulin administered, they do not provide information about the increased insulin resistance that stroke patients may experience after meals, at night, and dawn." (PMID 38989392, 2024). "Similarly, the thiazolidinediones, despite being potent insulin sensitizers and conferring stroke benefits, are not widely used due to issues with weight gain and edema." (PMID 36845885, 2023). "However, the role of subcutaneous insulin therapy for DKA should be reserved for mild cases with no complicated underlying diseases like acute kidney injury, myocardial infarction or stroke." (PMID 35274050, 2022). "Of note, the change in GS fractional activity in the nonparetic muscle was not related to M, whereas the change in GS fractional activity during the clamp in the paretic samples was related to M, creating different contributions of affected and nonaffected stroke muscle to systemic insulin action." (PMID 33375333, 2020). "Among the 3,956 T2DM patients without stroke, 2,702 (68.30%) patients used antihypertensive drugs, 562 (14.21%) patients used lipid-lowering drugs, 1,021 (25.81%) patients used aspirin, and 674 (17.04%) patients used insulin." (PMID 32982965, 2020). "A stroke can lead to reduced mobility affecting skeletal muscle mass and fatty infiltration which could lead to systemic insulin resistance, but this has not been examined and the mechanisms are currently unknown." (PMID 33375333, 2020). "In addition, compared with the combined therapy users, the insulin-based users also had a lower incidence of these outcomes except for nonfatal stroke." (PMID 30349614, 2018). "This may in part explain the negative results of published insulin trials, which generally included patients < 24 h post-stroke." (PMID 29777362, 2018). "Non-inferiority was confirmed for Insulin degludec regarding the primary endpoint non-fatal stroke." (PMID 29020969, 2017). "Post-stroke delay of MRI (p = 0.11) and insulin regimen (p = 0.90) were not significant." (PMID 25793765, 2015). "Only fasting insulin, but not glucose or HbA1c, was associated with incident CHD and stroke." (PMID 17760500, 2007).
Stroke (continued). "The metabolic mechanisms specifically responsible for semaglutide-improved stroke recovery are hard to pinpoint because it is essentially impossible to separate the effects of any treatment targeting body weight without also affecting glucose and insulin sensitivity." (PMID 41094027, 2026). "Similarly, insulin administration did not seem to affect the incidence of stroke." (PMID 39407846, 2024). "The use of antiplatelet agent did not modify the event rates for CAD-T2DM without prior MI or stroke patients, but was associated with a higher risk in the THEMIS-like population, and was probably more a proxy of disease severity as for diuretics and insulin above." (PMID 34823531, 2021). "The incidence rate of stroke was 14.64/1000 person – year (95% CI 10.74–19.97) (IRR 2.13 when Type 2 DM (+) group under human or analogous insulin treatment was compared with Type 2 DM (+) group without treatment with human or analogous insulin, 95% IC 1.60–2.80)." (PMID 30621603, 2019). "However, some studies indicated that high admission glucose level signified the severity of stroke but it was not a predictive factor for prognosis of stroke, and early intensive insulin therapy had failed to improve functional outcome after stroke in previous studies." (PMID 31836800, 2019). "We found a lower incidence of MACEs including nonfatal MI, nonfatal stroke, cardiac death, any death, amputation and heart failure for admission rate among the patients who received DPP4i-based therapy than in those treated with combined DPP4i- and insulin-based therapy." (PMID 30349614, 2018). "These analyses also showed that RPC-reactive IgG levels were lower in DR patients who used insulin than those who did not (p = 0.0152), that serum C3a levels were elevated in DR patients who had renal problems (p = 0.0348) and reduced in the sera of the two DR patients who had stroke (p = 0.0086)." (PMID 26839120, 2016). "In light of these results and the new Cochrane database literature review, we hypothesized that intensive insulin regimen is not efficient because it does not “save” critically relevant regions from damage in the first hours of stroke onset despite a better glucose control." (PMID 25793765, 2015). "If so, increased vulnerability to stroke injury in rodents fed a high fat diet, either in the presence (as we have observed) or absence of STZ/NA (as others have observed), may not necessarily be the result of lower brain EETs, but rather to differences in insulin resistance and glycemic status." (PMID 24824753, 2014). "Sensitivity analyses showed that most results of the associations between TyG and all-cause/cause-specific mortality were robust in T2DM patients without CHF, without CAD, without stroke, without CKD, or without insulin treatment at baseline." (PMID 38281973, 2024). "The 10-year risks of nonfatal stroke in OAD, insulin and OAD plus insulin groups were 3.0%, 3.4%, and 4.3%, respectively." (PMID 38263010, 2024). "In addition, more were likely to have had a previous stroke and myocardial infarction, and to have more prescriptions for anti-platelet agents, ACEIs/ARBs, beta-blockers, dihydropyridine calcium channel blockers, diuretics, cilostazol and insulin compared to the patients in the non-DVT group." (PMID 33850207, 2021). "Notably, the continuous insulin infusion therapy (CIIT) group showed no cases of in-hospital mortality, postoperative stroke, myocardial infarction, multiple organ failure, gastrointestinal bleeding, or need for extracorporeal hemocorrection." (PMID 40364261, 2025). "First, limited by human, material, and financial resources and other factors, and due to the absence of fasting insulin measurement and nonevaluation of HOMA-IR in the Kailuan Study, it was impossible to compare the differences between HOMA-IR and TyG index on early-onset stroke." (PMID 36631854, 2023).
Stroke (continued). "The method of the measurement of insulin sensitivity may largely influence the results, as insulin sensitivity measured with hyerinsulinemic-euglycemic clamp, but not fasting insulin, was a predictor of CHD and stroke/transient ischemic attack." (PMID 35439985, 2022).
Abdominal obesity (507 papers, 2005 to 2026). Excessive fat around the stomach and abdomen. "Previous studies have demonstrated that estrogens increases insulin sensitivity and decreases the risk of central obesity." (PMID 40313487, 2025). "Small increments in abdominal obesity in weight-recovered patients are, however, associated with decreased insulin sensitivity." (PMID 40422864, 2025). "R2 = 0.388) identified HbA1c, insulin, and diastolic BP as independent predictors, which aligns with the known pathophysiology of abdominal obesity and metabolic risk." (PMID 41002975, 2025). "Patients with central obesity are commonly resistant to insulin, a metabolic condition closely associated with NAFLD and reduced HRQoL, functional capacity and energy." (PMID 38709751, 2024). "For example, abdominal obesity is more closely associated with IR and metabolic dysfunction than peripheral obesity because it affects insulin metabolism by altering the release of fatty acids." (PMID 38970059, 2024). "It significantly contributes to adverse outcomes for their infants, affecting the time of birth, the birth weight, and cardiometabolic risk factors such as blood pressure, body mass index (BMI), abdominal obesity, lipid profiles, glucose, and insulin." (PMID 38791492, 2024). "Abdominal obesity is associated with elevated insulin concentrations in younger age groups and impaired glucose control in middle-aged groups." (PMID 39010068, 2024). "Endocrine changes related to central obesity include dysregulation of hypothalamic–pituitary–adrenal axis and alteration of the hormone levels (e.g., cortisol, leptin, and insulin), which are implicated in the control of mood and emotion." (PMID 38418418, 2024). "It has been suggested that high chronic insulin secretion leads to beta cell dysfunction, increased central obesity, and a higher risk of IR." (PMID 36624389, 2023). "Another cross-sectional study of community-dwelling older men observed that higher levels of MVPA and lower levels of sedentary behaviour were associated with better metabolic health in terms of central obesity, insulin level, and MetS." (PMID 35684102, 2022). "The increase in abdominal obesity associated with AGHD is likely to contribute to the reduced insulin sensitivity observed in some people with AGHD." (PMID 35761982, 2022). "Our results agree with the notion that high BMI and central obesity cause exaggerated insulin responses in PCOS women." (PMID 35646110, 2022). "Recent studies demonstrated that the methylation of ABCG1, CPT1A, and SREBF1 genes was associated with some cardio-metabolic risk factors including total cholesterol and insulin levels, as well as anthropometric indices of general and abdominal obesity." (PMID 35551677, 2022). "On the one hand, abdominal obesity has been strongly associated with insulin sensitivity and the mechanistic links are considered multifactorial." (PMID 36387872, 2022). "Previous studies have shown that consumption of betel quid was associated with central obesity as well as impaired insulin signaling and lipid storage." (PMID 35223941, 2022). "These strategies would include targeting weight loss, reducing central obesity and more importantly preferential selection of insulin sensitizing agents such as metformin or pioglitazone to ameliorate IR in newly diagnosed patients with higher BMI and WC." (PMID 33788827, 2021). "Further, in agreement with the literature and existing epidemiological studies we assumed abdominal obesity to mediate the association between nocturnal sleep duration and insulin resistance." (PMID 32603369, 2020). "Other authors have shown that eating six times per day reduces fasting insulin levels compared with eating three times per day, and a lower number of daily eating episodes has been associated with abdominal obesity and high levels of triglycerides." (PMID 33396200, 2020).
Abdominal obesity (continued). "In Models 3 and 4, hs-TnT, fasting glucose, 120 min glucose, fasting insulin, 120 min insulin, and indicators of abdominal obesity were associated with LVH." (PMID 32384681, 2020). "The final aim was to examine the extent to which abdominal obesity, indexed by waist circumference, affects the association between physical activity and insulin resistance." (PMID 33376604, 2020). "While the increased TG/HDL-C represented central obesity, which is directly associated with insulin resistant by altering secretion of different adipocytokines namely adiponectin, leptin, resistin and visfatin." (PMID 31640743, 2019). "LPIN1 plays a role in abdominal obesity, insulin sensitivity, and hypertriglyceridemia and it is associated to blood pressure regulation, especially in men." (PMID 31333395, 2019). "Increased insulin sensitivity after RE has been shown to be associated with a concomitant decrease of visceral and abdominal subcutaneous adiposity or abdominal obesity." (PMID 30621076, 2019). "Abdominal obesity leads to reduction of hepatic and insulin sensitivity, as visceral adipose tissue is highly resistant to insulin and susceptible to lipolysis, thus producing excess free fatty acids than adipose tissue in other sites." (PMID 31850288, 2019). "In this study, our findings are based on the screening of insulin and 11 adipokines to examine the interaction of central obesity and the clustering of the other 4 MetS risk factors on circulatory proinflammatory and anti-inflammatory adipokines." (PMID 30114249, 2018). "Treatment with a combination of multiple daily insulin injections and oral antidiabetic agents was associated with abdominal obesity in this study." (PMID 28588898, 2017). "Limited evidence suggests that exercise-induced improvement in insulin sensitivity is associated with reductions in abdominal obesity." (PMID 27936206, 2016). "Abdominal obesity remained significantly associated with a higher eGFR among non-Hispanic whites [β = 2.5 (1.2), p = 0.04], even in the model with insulin sensitivity [β = 3.4 (1.3), p = 0.01]." (PMID 27224643, 2016). "We found that insulin was strongly associated to all traits individually more intensely than HbA1c and glucose and, in particular, to abdominal obesity." (PMID 26241903, 2015). "It is established that abdominal obesity is associated with decreased glucose tolerance, alterations in glucose insulin homeostasis, reduced metabolic clearance of insulin, and decreased insulin-stimulated glucose disposal." (PMID 27398399, 2014). "It is true that over-expression of 11β-HSD1 gene (Hsd11b1) in the fat tissue of mice caused central obesity, disturbed lipid profiles and insulin resistance." (PMID 23533564, 2013). "In a previous study we found a genetic variant of the SCD-1 gene to be associated with the degree of abdominal obesity and insulin sensitivity in elderly men." (PMID 23298201, 2013). "Hypertriglyceridemic-waist phenotype would first be considered as a surrogate marker for a particularly deleterious dyslipidemic, insulin-resistant and pro-inflammatory profile, associated with abdominal obesity." (PMID 23241342, 2012). "Adult women of short stature (height ≥ 25 th percentile) and suffering from obesity were examined to investigate the association between abdominal obesity and resistance to insulin." (PMID 21776204, 2011). "This postprandial hypertriglyceridaemia is linked with increased cardiovascular risk, and associated with abdominal obesity and with increased liver fat and hepatic insulin resistance, as can be reflected by elevated γ-glutamyl transferase." (PMID 21162746, 2010). "From a physiological standpoint, the association between abdominal obesity and suicidal ideation may be explained by several mechanisms, including hormonal dysregulation, insulin resistance, and chronic inflammation." (PMID 40092916, 2025).
Abdominal obesity (continued). "Aging leads to reduced insulin secretion, decreased glucose tolerance, and increased IR.Aging-associated changes, such as sarcopenia, excess adiposity, osteoporosis, central obesity, oxidative stress, mitochondrial dysfunction, and altered metabolism, occur in both muscle and liver tissues." (PMID 41567335, 2025). "Furthermore, regular physical activity has been shown to improve insulin sensitivity and promote weight loss, which is particularly important in individuals with central obesity, a key component of MetS." (PMID 40137394, 2025). "In addition, central obesity increases oxidative stress in the body, and oxidative stress can induce IR by impairing insulin signaling and causing dysregulation of adipokines." (PMID 38951821, 2024). "The soluble fibers of fruits, vegetables, and seaweed may reduce the risk of abdominal obesity by slowing gastric emptying and increasing postprandial glucose levels and insulin sensitivity." (PMID 37297392, 2023). "Additionally, central obesity is associated with higher levels of free fatty acids, which can interfere with insulin metabolism, leading to hyperinsulinaemia." (PMID 38110373, 2023). "Low aerobic fitness in children and adolescents is associated with a higher prevalence of cardiometabolic risk factors (abdominal obesity, elevated blood pressure, increased levels of insulin, glucose and plasma lipids, increased IR prevalence, and enlarged left ventricle of the heart)." (PMID 33494341, 2021). "The best-characterized association is between abdominal obesity and disturbed insulin metabolism, which may influence cancer risk through cell proliferation and apoptosis." (PMID 33924417, 2021). "Abdominal obesity may cause fat cells to release pro-inflammatory chemicals, leading to insulin insensitivity." (PMID 33679223, 2021). "Therefore, numerous metabolic risk factors, such as resistance to insulin, hyperglycemia, abdominal obesity, and hyperuricemia, are considered to be early triggers for the mobilization of endothelial progenitor cells from bone marrow and peripheral tissue." (PMID 32351973, 2020). "Furthermore, it has been described that SFAs can cause abdominal obesity due to impaired insulin sensitivity, although the results are inconclusive." (PMID 32630591, 2020). "Other studies reported that the presence of high variance in sleep duration was associated with adverse metabolic outcomes (altered insulin, low-density lipoprotein and high-sensitivity C-reactive protein plasma levels) and abdominal obesity in children and adolescents." (PMID 31366143, 2019). "Insulin is one of the most important and studied growth factor correlated to prostate cancer as well as MS, in fact, men with high serum insulin levels, as well as abdominal obesity associated with high waist-to-hip ratio (WHR) have a greater risk of prostate cancer incidence." (PMID 28389628, 2017). "The purpose of this ancillary study is to identify whether and to what extent CRF and abdominal obesity mediate the association between exercise and insulin sensitivity in older adults." (PMID 27936206, 2016). "Abdominal obesity in young adults, especially in Mexican-Americans, is independently associated with albuminuria even with normal blood pressures, normoglycemia and normal insulin levels." (PMID 27224643, 2016). "Abdominal obesity in young adults, especially in Mexican-Americans, is independently associated with early markers of kidney dysfunction even in individuals with normal blood pressures, glucose levels and insulin sensitivity." (PMID 27224643, 2016). "While being unproven, this may partly explain higher susceptibility to abdominal obesity at lower BMI and reduced muscle mass with increased insulin resistance in Asian compared with Caucasian populations." (PMID 24744783, 2014). "In addition, TRAIL levels were also associated with fasting insulin levels, a strong correlate of adiposity and in particular central obesity." (PMID 23472162, 2013).